TRPV2 (transient receptor potential cation channel subfamily V member 2)
Diseases named in the same sentence as TRPV2 in open-access papers (continued):
Sharing a sentence is not in itself a finding about the gene and the disease.
Stroke (3 papers, 2023 to 2025). Sudden impairment of blood flow to a part of the brain due to occlusion or rupture of an artery to the brain. "Regulation of Ca2+ signaling in astrocytes is a promising strategy for stroke, and TRPV2 is an important osmotic balance regulator, mainly expressed in cortical astrocytes." (PMID 36527242, 2023). "Based on our research, allicin, when used therapeutically, may be delivered into the brain by TRPV2 to improve post-stroke functional impairment, including behavior and the cerebral infarction area." (PMID 37673878, 2023). "Increased expression or activation of TRPM2, TRPV2, and TRPV4 was observed in stroke." (PMID 41399206, 2025). "Therefore, inhibition of TRPM2, TRPV2, and TRPV4 channels emerges as promising anti‐neuroinflammatory targets for stroke treatment." (PMID 41399206, 2025).
ulcerative colitis (3 papers, 2018 to 2025). An inflammatory bowel disease involving the mucosal surface of the large intestine and rectum. "Low expression levels of TRPV2 were identified in both UC and normal intestine tissue and there are no published data referring to the contribution of TRPV2 in human ulcerative colitis." (PMID 29914124, 2018). "The aim of this study was to evaluate the expression levels of TRPV1, TRPV2, TRPV3 and TRPV4 in mucosa epithelial cells of colonic biopsies from patients with ulcerative colitis (UC) in comparison to colonic resections from non-IBD patients (control group)." (PMID 29914124, 2018).
advanced heart failure (2 papers, 2023 to 2025). Patients with advanced heart failure have severe limitations, experiences symptoms even while at rest and are mostly bedbound patients. "The results of this study suggested that tranilast has a long-term, stable TRPV2 inhibitory effect that prevents worsening of cardiac function and cardiac death and can be administered relatively safely even to patients with MD and advanced heart failure." (PMID 39789553, 2025).
basophilic leukemia (2 papers, 2017 to 2025). "We used rat basophilic leukemia (RBL) cells in which we had previously established a CRISPR/Cas9-mediated TRPV2 knockout (KO) line." (PMID 41511297, 2025). "For instance, the transcripts of TRPV1, TRPV2, TRPV4, and TRPV6 were identified in RBL-2H3 cells (rat basophilic leukemia cell line), TRPV1, TRPV2, and TRPV6 in HMC-1, and TRPV2 in human lung, skin, and cord blood-derived mast cells." (PMID 28158279, 2017).
brain neoplasm (2 papers, 2018 to 2022). A neoplasm (disease) that involves the brain. "Since the MYTH was performed using a human brain cDNA library, we intersected both neoplasms and CNS diseases to identify the brain neoplasms more associated with our TRPV2 interactome." (PMID 29719613, 2018). "Among these TRP family genes, it has been shown previously that TRPV2 in brain tumours, TRPV6 in PRAD, and TRPC6 in STAD promote tumour progression—which validates our analysis." (PMID 35493463, 2022). "This analysis identified neoplasms and nervous system diseases as the most associated diseases with the TRPV2 interactome, and highlighted a set of genes previously associated to brain neoplasms, such as: ABR, FGF1, KCNJ10, PEBP1, PLP1, SDC3 and TRPV2." (PMID 29719613, 2018). "The most associated diseases with the TRPV2 interactome were neoplasms and diseases from the nervous system, and ABR, FGF1, KNJ10, PEBP1, PLP1, SOC3, and TRPV2 were found to be associated with brain neoplasms." (PMID 29719613, 2018).
cardiac hypertrophy (2 papers, 2017 to 2019). "A knockout of TRPV2 protects hearts against pressure-overload-induced hypertrophy, but produces no protection against AngII or β-adrenergic activation-induced hypertrophy, indicating that TRPV2 regulates cardiac hypertrophy through stretch activation." (PMID 31547577, 2019). "Moreover, TRPV2 and TRPA1 seem to be involved in insulin secretion, TRPV1 and TRPV2 in heart hypertrophy, TRPV3 in skin disorders, TRPV1 and TRPA1 in airway irritation and cough, and TRPV1, TRPV2 and TRPA1 in cancer." (PMID 28333079, 2017).
cognitive deficits (2 papers, 2022 to 2025). "The cation channel TRPV2 may mediate the pathological changes in mild cognitive impairment." (PMID 35628181, 2022). "Previous research has shown that the inhibition of TRP channels, including TRPV2 and TRPM4, can mitigate cognitive deficits in a range of disease contexts models." (PMID 40340504, 2025).
dysferlinopathy (2 papers, 2020 to 2025). "Cx43 HCs, P2X7 receptors, and the TRPV2 channel have all been shown to be present in muscular biopsies from dysferlinopathy patients and are permeable to Ca2+." (PMID 41155239, 2025).
epilepsy (2 papers, 2020 to 2024). A brain disorder characterized by episodes of abnormally increased neuronal discharge resulting in transient episodes of sensory or motor neurological dysfunction, or psychic dysfunction. "According to electrophysiology studies, CBD activates rat TRPV2 with an EC50 of 3.7 μM, although the link with epilepsy is much less direct than that for sodium channels." (PMID 33089780, 2020).
fibrosarcoma (2 papers, 2020 to 2021). A malignant mesenchymal fibroblastic neoplasm affecting the soft tissue and bone. "Additionally, Rac1 is able to dictate intracellular trafficking of TRPV2 in fibrosarcoma cells, implicating a central role of these Rho GTPases in TRPV2 regulation." (PMID 34356643, 2021).
gout (2 papers, 2020 to 2025). A condition characterized by painful swelling of the joints, which is caused by deposition of urate crystals. "TRPV2 loss could be, at least partially, rescued by TRPV2 agonists, such as cannabidiol and the anti-gout medication probenecid." (PMID 40558483, 2025).
lung carcinoma (2 papers, 2022). "High expression of TRPV2 correlates with better overall survival of lung cancer patients." (PMID 35267489, 2022). "Further, we used a KM plotter to analyze overall survival of patients based on TRPV2 expression and observed that lung cancer patients with higher expression of TRPV2 has a significantly better overall survival (p = 4.3 × 10−6) compared to patients with low TRPV2 expression." (PMID 35267489, 2022).
lymphoma (2 papers, 2014 to 2020). A malignant (clonal) proliferation of B- lymphocytes or T- lymphocytes which involves the lymph nodes, bone marrow and/or extranodal sites. "Another Ca2+ channel, the transient receptor potential cation channel subfamily V member 2 (TRPV2), showed lower response to membrane stretching when silenced in Jurkat (human lymphoma CD4+ cells)." (PMID 32384769, 2020).
mastitis (2 papers, 2022 to 2025). Inflammation of breast tissue during lactation or postpartum due to an obstructed duct or infection. "TRPV2 has been reported as associated with resistance to mastitis as well as milk yield and milking rate." (PMID 40805037, 2025). "Previous studies showed that ELMO and TRPV2 are associated with resistance to mastitis in dairy cattle." (PMID 35739877, 2022).
neuropathy (2 papers, 2012 to 2017). A disorder affecting the nervous system that manifests with pain, tingling, numbness, and/or muscle weakness. "Because selective TRPV2 antagonists are not commercially available, further mechanistic studies including TRPV2 knockout mouse might be needed to determine the exact involvement of TRPV2 in cisplatin-induced neuropathy." (PMID 29326595, 2017). "Moreover, there was no change in the densities of TRPV2(+) neurons and the ratios of TRPV2/CGRP during RTX-induced neuropathy, indicating TRPV2 are not responsible for the thermal compensation in RTX-induced neuropathy." (PMID 23209829, 2012).
osteosarcoma (2 papers, 2020 to 2025). A usually aggressive malignant bone-forming mesenchymal neoplasm, predominantly affecting adolescents and young adults. "The U2OS osteosarcoma cells overexpressing TRPV2 when receiving TRPV2–PCNH+laser resulted in downregulated β-catenin (associated with carcinogenesis) expression in contrast to the non-laser-treated TRPV2–PCNH and control group." (PMID 40548119, 2025). "In order to explore the effect of TRPV2 in cell morphology, we expressed TRPV2-GFP in different non-neuronal cell lines like ChoKI (Chinese hamster ovary), HaCaT (keratinocyte cell line), HEK (kidney cell line) and SaOS (primary osteosarcoma)." (PMID 32985655, 2020).
ovarian carcinoma (2 papers, 2021 to 2022). A malignant neoplasm originating from the surface ovarian epithelium. "Homeostasis of intracellular Ca2+ is essential for cisplatin-induced apoptosis in ovarian cancer, and it is suggested in some studies that cisplatin resistance is supported by Ca2+ efflux through TRPV2." (PMID 35267489, 2022).
atopic dermatitis (1 paper, 2022). "In contrast, in skin biopsies from patients with atopic dermatitis, TRPV1 and TRPV2 were upregulated and TRPV3 and TRPM8 were downregulated." (PMID 36552866, 2022). "In summary, although TRPV2 was downregulated in pruritic skin regions of psoriasis and phymatous rosacea and TRPV3 was downregulated in skin biopsies from patients with atopic dermatitis, TRP channels appear to be upregulated in most skin disease studies." (PMID 36552866, 2022).
atrial fibrillation (1 paper, 2022). A disorder characterized by an electrocardiographic finding of a supraventricular arrhythmia characterized by the replacement of consistent P waves by rapid oscillations or fibrillatory waves that vary in size, shape and timing and are accompanied by an irregular ventricular response. "We aimed to characterize the expression levels of TRPV2 mRNA in peripheral blood mononuclear cells (PBMCs) with/without early recurrence of atrial fibrillation (ERAF) after radiofrequency catheter ablation (RFCA), and to find a reliable predictor for ERAF." (PMID 36513971, 2022).
chronic hepatitis (1 paper, 2014). An active inflammatory process affecting the liver for more than six months. "TRPV2 overexpression at both the mRNA and protein levels was found in cirrhotic livers compared with those with chronic hepatitis." (PMID 24709905, 2014).
chronic myeloid leukemia (1 paper, 2022). "TRPV2, TRPM7 and TRPC1 have been studied in chronic myeloid leukemia (CML) cell lines (K-562, KU812, MOLM-6 and 32D-p210)." (PMID 36330491, 2022).
Cirrhosis (1 paper, 2023). A chronic disorder of the liver in which liver tissue becomes scarred and is partially replaced by regenerative nodules and fibrotic tissue resulting in loss of liver function. "Increased TRPV2 protein expression was found in 84% of cirrhosis cases compared to normal liver." (PMID 37240443, 2023).
congenital glaucoma (1 paper, 2024). "TRPV2-IR was heavier in the GCL and ACL in the congenital glaucoma model DBA/2J (D2) mice, and the relative intensity was in the order of GCL≈ ACL > OPL≈OSL." (PMID 39606631, 2024).
Constipation (1 paper, 2021). Infrequent or difficult evacuation of feces. "Three genes, 5-HT receptor subtype 2a and 2c (Htr2a and Htr2c) and Transient receptor potential vanilloid 2 (Trpv2) were significantly upregulated in the constipation group in comparison to the control group." (PMID 33441874, 2021). "An ion channel, Trpv2 also showed a significant elevation in the bladder following four days of constipation." (PMID 33441874, 2021).
demyelination (1 paper, 2022). "In the EAE model, in which demyelination foci are developed in the spinal cord accompanied by clinical symptoms of paralysis, we analyzed TRPV2 expression in spinal cord sections." (PMID 35408977, 2022).
demyelination disorders (1 paper, 2022). "Further studies on the expression of TRPV2 and its role in MS and other demyelinating diseases may unravel this question." (PMID 35408977, 2022).
depression (1 paper, 2024). "The discovery and validation of TRPV2, ZNF713, and CTSL as potential biomarkers offer a promising avenue for enhancing the precision of depression diagnosis and advancing our understanding of this complex disorder." (PMID 40226717, 2024). "Moreover, TRPV2 influences the ERK1/2-CREB-BDNF signaling pathway, which is involved in neuroplasticity and depression." (PMID 40226717, 2024).
Duchenne muscular dystrophy (1 paper, 2018). Duchenne muscular dystrophy (DMD) is a neuromuscular disease characterized by rapidly progressive muscle weakness and wasting due to degeneration of skeletal, smooth and cardiac muscle. "In addition, it has been reported that TRPV2 is involved in myotubes from patients with Duchenne muscular dystrophy." (PMID 29581825, 2018).
ependymoma (1 paper, 2021). A WHO grade II, slow growing tumor of children and young adults, usually located intraventricularly. "TRPV2, TRPV4, and TRPA1 were expressed to similar levels across the two ependymoma subgroups." (PMID 33477420, 2021).
experimental autoimmune encephalomyelitis (1 paper, 2022). An autoimmune demyelinating disease of the central nervous system that is produced experimentally in animals by the injection of homogenized brain or spinal cord in Freund's adjuvant. "Then, we characterized TRPV2 time-course expression in experimental animal models of hypomyelination (jimpy mice) and de-/remyelination (cuprizone intoxication and experimental autoimmune encephalomyelitis (EAE))." (PMID 35408977, 2022).
Failure to thrive (1 paper, 2021). Failure to thrive (FTT) refers to a child whose physical growth is substantially below the norm. "Interestingly, TRPV2 knockout mice have a reduced birth weight and are more susceptible to perinatal lethality, a feature that was attributed to prenatal events rather than post-natal failure to thrive." (PMID 33884443, 2021).
hearing loss (1 paper, 2019). "Based on these observations, it was suggested that TRPV3 and TRPV4 play an important role in neuroprotection while TRPV1 and TRPV2 are involved in the pathology of hearing loss." (PMID 31866822, 2019).
infarction (1 paper, 2017). A localised pathological necrosis of tissue resulting from obstruction of the blood supply usually by a thrombus, an embolus, or vascular torsion. "In the case of acute MI, we anticipate that similar numbers of monocytes are recruited to the infarct area, however the migratory and potentially the phagocytic activity of the mature TRPV2-KO macrophages are moderated, leading to an improved healing." (PMID 28481959, 2017). "Next, in order to carefully assess the potential effect of TRPV2 macrophages on cardiac recovery following an acute MI, 150,000 WT or KO macrophages were IV administered to TRPV2-KO mice, two days post infarction, via the jugular vein." (PMID 28481959, 2017).
infertile (1 paper, 2021). "This situation causes the appearance of a CD206+MHC II+ subpopulation of TRPV2+ macrophages, which appear to be part of the inflammatory events in AROM+ animals and may play roles in testicular dysfunction and infertility." (PMID 33946947, 2021). "In general agreement with this assumption, we found that both the aromatase inhibitor treatment, as well as crossings of AROM+ with ERαKO, not only, as expected, rescued the infertile phenotype and reverted macrophage and inflammation markers, but also reduced TRPV2 and NOX2 levels." (PMID 33946947, 2021). "It is likely that the testicular TRPV2+ macrophages are part of an inflammatory cascade in the testes of AROM+ and thereby are involved in the development of infertility." (PMID 33946947, 2021).
invasive carcinoma (1 paper, 2016). A carcinoma that is not confined to the epithelium, and has spread to the surrounding stroma. "Staining for LL37 and TRPV2 was found in 60 and 42 invasive carcinomas, respectively." (PMID 26993604, 2016).
keloid (1 paper, 2026). An irregularly shaped, elevated mark on the skin caused by deposits of excessive amounts of collagen during wound healing. "Compounds such as the TRPV1 blocker asivatrep and the TRPV3 inhibitor KM-001 have shown significant antipruritic effects in skin disorders, while tranilast, a TRPV2 antagonist, has provided concrete clinical evidence for TRP modulation in treating keloids." (PMID 41596464, 2026).
left ventricular hypertrophy (1 paper, 2019). Enlargement of the LEFT VENTRICLE of the heart. "TRPV2 is also significantly upregulated in wild-type mice subjected to TAC, whereas the absence of functional TRPV2 reduces significantly the left ventricular hypertrophy after TAC, suggesting a role of TRPV2 in the development of cardiomyocyte hypertrophy because of an increased afterload." (PMID 30881310, 2019).
lung adenocarcinoma (1 paper, 2022). A carcinoma that arises from the lung and is characterized by the presence of malignant glandular epithelial cells. "High expression of TRPV2 is found in NSCLC cell lines and in lung adenocarcinoma patients, where it is associated with poor overall survival." (PMID 35267489, 2022). "We further discovered that CBD mediates its anti-cancer effects in part via an ion channel receptor, TRPV2, present on lung adenocarcinoma." (PMID 35267489, 2022). "Importantly, our data show that CBD mediates these effects through TRPV2, which is highly expressed in lung adenocarcinomas." (PMID 35267489, 2022). "Moreover, we show that CBD acts through Transient Receptor Potential Vanilloid-2 (TRPV2) to induce apoptosis, where TRPV2 is expressed on human lung adenocarcinoma tumors." (PMID 35267489, 2022).
lymph node metastasis (1 paper, 2019). "A univariate analysis of survival (5-year overall survival) showed that pathological venous invasion, pathological lymph node metastasis, and the strong expression of TRPV2 were significant." (PMID 31690728, 2019).
male infertility (1 paper, 2021). The inability of the male to effect fertilization of an ovum after a specified period of unprotected intercourse. "This study describes, for the first time, the expression pattern of the mysterious cation channel TRPV2 in murine testis with special regard to macrophages in the case of WT and the well-established model for male infertility AROM+, taking into account age-related changes." (PMID 33946947, 2021).
mantle cell lymphoma (1 paper, 2014). Mantle cell lymphoma is a rare form of malignant non-Hodgkin lymphoma affecting B lymphocytes in the lymph nodes in a region called the ``mantle zone''. "Aberrant TRPV2 expression in B lymphocytes from mantle cell lymphoma (MCL) cell lines and tissues has been reported." (PMID 24709905, 2014).
metastatic melanoma (1 paper, 2023). A melanoma that has spread from its primary site to another anatomic site. "In metastatic melanoma models, we observed that TRPV2 activity regulates calpain activation and the ensuing cleavage of talin." (PMID 36744297, 2023). "In unstimulated metastatic melanoma cells, a subset of TRPV2 channels is, therefore, addressed to the PM and is active, allowing Ca2+ entry." (PMID 36744297, 2023). "In the noninvasive cell line, TRPV2 overexpression induced a 2‐fold increase in calpain basal activity compared to MOCK cells, while reciprocally TRPV2 silencing in both metastatic melanoma cell lines halved the protease activity." (PMID 36744297, 2023). "Hence, TRPV2‐mediated activation of calpain promoting the spatiotemporally regulated proteolysis of talin, and the resulting adhesion dynamic could be an adaptive mechanism specific to cells endowed with fast migrating features such as the metastatic melanoma cells." (PMID 36744297, 2023).
metastatic prostate carcinoma (1 paper, 2021). A carcinoma that arises from the prostate gland and has spread to other anatomic sites. "In metastatic prostate cancer, increased expression of the transient receptor potential cation channel subfamily V member 2 (TRPV2) resulted in enhanced cell motility through the invasion associated enzymes MMP9 and cathepsin B." (PMID 33802790, 2021).
multiple sclerosis (1 paper, 2022). A progressive autoimmune disorder affecting the central nervous system resulting in demyelination. "TRPV2 expression was altered in human samples of multiple sclerosis (MS) patients." (PMID 35408977, 2022).